CAST (calpastatin)
Diseases named in the same sentence as CAST in open-access papers (continued):
Sharing a sentence is not in itself a finding about the gene and the disease.
infection (continued). "Since CAST mice display several similarities to human infection, they could potentially serve as a better model for evaluation of next generation therapeutics and vaccines against SARS-CoV-2." (PMID 39149485, 2024). "By 6 weeks post-infection the ∆bioA mutant had also been largely cleared from the lungs of CAST." (PMID 35112666, 2022). "In addition, CAST/EiJ mice showed the highest number of DEPS after infection in blood and lungs." (PMID 26921172, 2016). "Strikingly, infection of the “wild-derived” strains among CC founders, WSB, PWK and CAST, induced variable disease phenotypes for each strain." (PMID 39149485, 2024). "XIAP is maintained at high levels in LVS-infected PMNs via increased expression of the BIRC4 gene and by upregulation of calpastatin (CAST), which prevents calpain-mediated XIAP degradation in healthy cells and during LVS infection." (PMID 35873156, 2022). "In the context of SARS-CoV, infection of various mouse strains (PWK/PhJ (PWK), CAST/EiJ (CAST), 129S1/SvImJ (129/S1), and WSB/EiJ (WSB) mice) appears to be associated with differential expression of several hundred lncRNAs." (PMID 36367091, 2022). "Caspase activation is inhibited in LVS infection by the concerted actions of XIAP, cIAPs and calpastatin." (PMID 35693822, 2022). "At an increased infection dose of 2 × 103 FFU all mice from highly and intermediate susceptible strains (A/J, C57BL/6J, 129S1/SvImJ, NOD/ShiLtJ, CAST/EiJ and WSB/EiJ) succumbed to the infection." (PMID 26921172, 2016). "Some strains, such as 129S1/SvImJ and CAST/EiJ, had high levels of MA15 RNA on day 4 after infection whereas others, such as NZO/HILtJ and NOD/ShiLtJ, had low levels of MA15 RNA." (PMID 24902603, 2014). "Among mice infected with PR8 at day 2 after infection, IFNG was only expressed in C57BL/6J, CAST/EiJ, PWK/PhJ, and WSB/EiJ, whereas it was expressed in all strains except CAST/EiJ on day 4 after infection." (PMID 24902603, 2014). "The most notable change in a cellular population found in the CAST mice was an increase in the frequency but not the total cell number of interstitial macrophages, increasing over the course of infection, which was not seen in B6J or K18-hACE2 mice." (PMID 39149485, 2024). "To address this, we infected K18-hACE2 and CAST mice with 2×104 PFU of Beta VOC and 1 day post infection, mice were treated with a protease inhibitor (PF-1332) at 500 mg/kg/day or vehicle for the first 4 days of infection." (PMID 39149485, 2024). "Interestingly, Wfdc17 was up-regulated in lungs of C57BL/6J, 129S1/SvlmJ and PWK/PhJ after infection, but not in CAST/EiJ which is consistent with the observed increase of infiltrating macrophages in CAST/EiJ lungs." (PMID 26921172, 2016). "Also, the Wfdc17 gene, encoding the AMWAP protein (activated microglia/macrophage whey acid protein domain protein), was not expressed in CAST/EiJ mice before and after infection." (PMID 26921172, 2016). "However, compared with the mock-GRV-infected cells, the expression of full-length (FL) calpastatin-GRV in infected CD4+ T cells was not maintained, and the positive cells had almost disappeared by day 7 after infection." (PMID 22046434, 2011).
neurodegenerative disease (6 papers, 2018 to 2026). A disorder of the central nervous system characterized by gradual and progressive loss of neural tissue and neurologic function. "The protective effects of calpain inhibition via the genetic enhancement of CAST have been observed in several other neurodegenerative diseases, such as AD, PD, and ALS." (PMID 34489447, 2021). "Engaging this system with pharmacological tools such as specific calpain inhibitors or compounds targeting activating pathways as well as genetic strategies, like overexpressing CAST or ablating calpain isoforms, showed phenotype-attenuating effects in models of neurodegenerative diseases." (PMID 35482253, 2022). "In the light of this study, the suggestive therapeutic strategy might be the prevention of the degradation of Calpain-CAST complexes and the inhibition of Calpain for the treatment of neurodegenerative diseases such as AD." (PMID 29875647, 2018). "Calpain inhibition by overexpression of CAST or pharmacological means has been proven effective in reducing levels of toxic fragments and aggregates of mutant proteins, thereby attenuating the overall pathology in models of neurodegenerative diseases including HD, MJD and PD." (PMID 35482253, 2022). "Further investigations on how the CAST–calpain–Drp1 cell death pathway is controlled and how the biological optimization of CHIR99021 may accelerate the discovery of therapeutic approaches to treat multiple neurodegenerative diseases are warranted." (PMID 34489447, 2021).
neurological disease (4 papers, 2017 to 2025). "While its protective role in calpastatin in cardiovascular and neurological disease is established.emerging evidence links abnormal calpastatin-mediated Ca2+ regulation to PE." (PMID 41162732, 2025). "Future studies will resolve the molecular interactions and signaling pathways by which CAST/ELKS regulate VGCCs and synaptic transmission in different synapses and their roles in neuronal circuit function and impact on neurological diseases." (PMID 29996090, 2018).
nephropathy (2 papers, 2016 to 2020). A nonspecific term referring to disease or damage of the kidneys. "Thus the severity of kidney disease increased with the number of CAST alleles in Tg-Sub-III and Tg-Sub-IV mice, demonstrating an additive effect (nonparametric p-value = 9x10—65x10-3)." (PMID 27736906, 2016).
metabolic disease (1 paper, 2024). A congenital disorder (due to inherited enzyme abnormality) or acquired (due to failure of a metabolically important organ) disorder resulting from an abnormal metabolic process. "For example, unlike C57BL/6 J mice, WD-fed A/J, BALB and CAST are often protected against hallmarks of WD-induced metabolic disease." (PMID 38961153, 2024).
CAST also shares sentences with these, for which no sentence is quoted: acute myelogenous leukemia (2 papers); amyloid (2); Hypertension (2); Insulin resistance (2); pancreatic adenocarcinoma (2); acute kidney injury (1); ankylosing spondylitis (1); autoimmune disorders (1); autosomal recessive congenital ichthyosis (1); bradyopsia (1); cancers of the bile duct (1); cerebral amyloid angiopathy (1); citrullinemia (1); colitis (1); cone-rod dystrophy (1); congenital stationary night blindness (1); corneal dystrophy (1); dilated cardiomyopathy (1); dyskeratosis congenita (1); ectodermal dysplasia (1); endotoxemia (1); gastrointestinal tumors (1); glaucoma (1); glomerulosclerosis (1); Hearing impairment (1); heart disease (1); Hepatic fibrosis (1); ichthyosis vulgaris (1); iridocyclitis (1); iris hypoplasia (1).
A further 34 diseases each share a sentence with CAST in 1 paper.